TUG1 (taurine up-regulated 1)
Diseases named in the same sentence as TUG1 in open-access papers (continued):
Sharing a sentence is not in itself a finding about the gene and the disease.
infection (4 papers, 2017 to 2024). The state of being infected such as from the introduction of a foreign agent such as serum, vaccine, antigenic substance or organism. "After infection with the IAV for 24 h, the expression of lncRNA TUG1 in pHBECs increased significantly, whereas the expression of miR-145-5p decreased significantly." (PMID 33841139, 2021).
neurodegenerative disease (4 papers, 2018 to 2024). A disorder of the central nervous system characterized by gradual and progressive loss of neural tissue and neurologic function. "Two lncRNAs (NEAT1 and TUG1) were found to be associated with neurodegenerative disease." (PMID 29653596, 2018). "Several identified lncRNAs play crucial roles in neuron function and maintenance in neurodegenerative diseases, such as Tug1, participating in normal photoreceptor development and contributing to rod differentiation and survival, and Meg3, regulating the process of light-induced retinal damage." (PMID 37811327, 2023).
neurological disorders (4 papers, 2018 to 2025). "Long non-coding RNA taurine up-regulated gene 1 (lncRNA TUG1) is widely expressed in adult brain and has been reported to participate in multiple biological processes associated with nervous system diseases." (PMID 31551710, 2019). "Additionally, considering the multifaceted roles of TUG1 in neurological diseases, developing personalized therapeutic strategies targeting TUG1 may hold significant clinical significance." (PMID 39595085, 2024).
cerebral artery (1 paper, 2024). "To compare the behavioral and histological differences in brain tissue ischemia between TUG1KO rats (TUG1+/−) and WT rats, we performed experiments on middle cerebral artery obstruction in the rats." (PMID 39595085, 2024).
gynecological tumors (1 paper, 2021). "In the subgroup analysis, we found that the high expression of TUG1 was related to poor OS of patients with gastrointestinal cancers (ESCC, GC, CRC, PC, HCC, and CCA), gynecological tumors (BC, OC, CC, and EC), hematological tumors (AML and NHL), urinary tumors (RCC, BLC, UC, and PCa), and OSA." (PMID 33747256, 2021).
hematological cancers (1 paper, 2022). "LncRNA Taurine-Upregulated Gene1 (TUG1), located on chromosome 22q12, a critical oncogenic lncRNA of human, has been proved to take part in hematological cancers." (PMID 35322118, 2022).
metabolic disorders (1 paper, 2020). "More recently, great attention has been paid to the probable role of two novel lncRNAs; metastasis-associated lung adenocarcinoma transcript 1 (MALAT1) and taurine upregulated gene 1 (TUG1) in the pathogenesis of metabolic disorders." (PMID 32368256, 2020). "Today, little is known about MALAT1 and TUG1 function and regulation in metabolic disorders." (PMID 32368256, 2020).
TUG1 also shares sentences with these, for which no sentence is quoted: adenocarcinoma (3 papers); diabetic cardiomyopathy (3); endometrial cancer (3); gallbladder carcinoma (3); heart failure (3); acute myocardial infarction (2); aortic valve calcification (2); gall bladder cancer (2); retinoblastoma (2); acute lymphoblastic leukemia (1); alcoholism (1); aortic aneurysm (1); aortic stenosis (1); autism (1); bladder tumors (1); bone disorder (1); bone sarcoma (1); bronchopulmonary dysplasia (1); cerebrovascular diseases (1); chronic lymphocytic leukemia (1); Cirrhosis (1); cutaneous melanoma (1); deep vein thrombosis (1); dyslipidemia (1); epilepsy (1); head and neck neoplasm (1); hypertrophic cardiomyopathy (1); in situ breast cancer (1); interstitial lung disease (1); invasive breast carcinoma (1).
A further 23 diseases each share a sentence with TUG1 in 1 paper.